ABCG1 (ATP binding cassette subfamily G member 1)
Diseases named in the same sentence as ABCG1 in open-access papers (continued):
Sharing a sentence is not in itself a finding about the gene and the disease.
melanoma (9 papers, 2017 to 2024). A malignant, usually aggressive tumor composed of atypical, neoplastic melanocytes. "In a recent study, global and myeloid deficiency of ABCG1 was shown to be associated with reduced melanoma and bladder tumor growth in mice fed a “western”-type diet." (PMID 29069761, 2017). "The mRNAsi results showed that elevated intracellular cholesterol was positively associated with melanoma stemness, through activation of DHCR24 in cholesterol biosynthesis or inhibition of efflux by ABCA1, and ABCG1." (PMID 38775844, 2024). "Here, we identified a tumor protective function against B16F10 melanoma and MB49 bladder cancer in mice with myeloid deficiency in ABCA1 (A1−M/−M) or ABCA1 and ABCG1 (DKO)." (PMID 29069761, 2017). "In human SK-MEL-30 melanoma cells treated with 250 ng/mL hGH in vitro increased expression of ABCB5, ABCB8, ABCG1 and ABCG2 RNA." (PMID 33291663, 2020). "ABCA1, ABCG1 (HDL receptor) and SRBP-1 (HDL receptor) are candidates for further investigation as potential mediators of apoA-I anti-tumor activity in B16F10 melanoma." (PMID 32477466, 2020). "Herein, we explored potential roles in melanoma tumorigenesis for host scavenger receptor class B, type 1 (SR-B1), and ATP-binding cassette transporters A1 (ABCA1) and G1 (ABCG1), all mediators of apoA-I and HDL sterol and lipid transport function." (PMID 29069761, 2017). "In this study we investigated the role of host cholesterol transporters ABCA1, ABCG1, and the HDL receptor SR-B1, on melanoma and bladder tumor growth." (PMID 29069761, 2017). "A query of human tumor transcriptomic data for 471 melanoma patients from The Cancer Genome Atlas (TCGA) dataset revealed a positive correlation of IGF1 and ABCC9, ABCG1, ABCB1, and ABCC4 with GHR expression, and ABCC1 with both GHR and IGF1R expression, supporting our observations." (PMID 35865483, 2022).
myocardial infarction (9 papers, 2017 to 2024). Gross necrosis of the myocardium, as a result of interruption of the blood supply to the area, as in coronary thrombosis. "Ser630Leu, g.−376C > T, and g.−311T > A variants of the ABCG1 predicted a risk of myocardial infarction." (PMID 34940525, 2021). "The ABCG1 polymorphism, g.-376C> T, resulted in a decreased ABCG1 mRNA expression, which increased the risks of CHD and myocardial infarction and resulted in shorter life expectancy in the general population." (PMID 39857239, 2024). "On the other hand, patients with the ABCG1-367G>A polymorphism (rs57137919) had a reduced risk of CHD and myocardial infarction (MI), and showed an association with CHD severity by angiography (multivessel CHD versus single-vessel CHD)." (PMID 39857239, 2024). "Blood DNA methylation levels in ABCG1 (cg06500161) are higher in subjects with previous hospitalized myocardial infarction compared with healthy controls." (PMID 34837967, 2021). "In contrast, ABCG1 polymorphism rs57137919 (−367G > A) showed a significantly decreased risk for CAD and myocardial infarction in a Han Chinese population." (PMID 34940525, 2021). "Functional enrichment analysis found that the methylation of ABCG1 methylation site cg06500161 may be associated with the significant lipid-lowering effects of lipid-lowering drugs and myocardial infarction related to the ABCG1 gene." (PMID 39200098, 2024).
hyperlipidemia (8 papers, 2013 to 2026). "Loss or impaired function of ABCA1 or ABCG1 in human or experimental rodents leads to hyperlipidemia, excessive cholesterol accumulation in peripheral tissues, and an overwhelming inflammatory response." (PMID 23878415, 2013). "Notably, metabolic DEGs such as ACSL1, ABCA1, ABCG1, ACAT2, ALOX5AP, PLA1A, and PPARG were elevated in hyperlipidemia." (PMID 39853712, 2025).
prostate carcinoma (7 papers, 2013 to 2026). A carcinoma that arises from epithelial cells of the prostate gland. "ABCG1 regulates cholesterol transport and membrane composition and has been implicated in the progression of ovarian and prostate cancers." (PMID 40804485, 2025). "Several lines of evidence have demonstrated that activation of p38 is able to up-regulate the expression of ABCA1 and ABCG1 in macrophages and prostate cancer epithelial cells." (PMID 35902881, 2022). "In contrast, prostate cancer tissues exhibited frequent deep deletions in ABCG2, ABCG1, ABCC4, ABCA2, ABCC2, ABCC7/CFTR, and ABCC9." (PMID 40641097, 2025). "In prostate cancer tissues, however, gene amplifications and deep deletions were most frequently detected in ABCG2 and ABCG1." (PMID 40641097, 2025). "Impaired LXR-mediated regulation of ABCA1 and ABCG1 involved in cholesterol efflux has been proposed as a defect in LnCaP and PC3 prostate cancer cell lines that contributes to cholesterol elevation." (PMID 23919967, 2013).
hepatocellular carcinoma (6 papers, 2012 to 2025). A malignant tumor that arises from hepatocytes. "ABCG1 upregulation was linked to oxaliplatin resistance in hepatocellular carcinoma while ABCG2 is known for promoting the efflux of a variety of substrates including cytotoxic agents." (PMID 37297005, 2023). "As a member of the ATP-binding cassette transporters, ABCG1 induces drug resistance in many cancers, including hepatocellular carcinoma and osteosarcoma, so we speculated that ABCG1 may also participate in TMZ resistance in GBM." (PMID 34079762, 2021). "More in-depth cholesterol-transport and membrane re-organization studies in macrophage or hepatocyte/hepatoma cell lines warrant further investigation and can provide sharper insight as to how these mutant SR-BI receptors behave when all efflux machinery (i.e. ABCA1 and ABCG1) is present." (PMID 23029167, 2012). "Contrarily, elevated cytoplasmic ABCG1 levels do not reliably predict outcomes in hepatocellular carcinoma (HCC) patients." (PMID 40520894, 2025).
osteosarcoma (6 papers, 2020 to 2025). A usually aggressive malignant bone-forming mesenchymal neoplasm, predominantly affecting adolescents and young adults. "Other work has correlated the expression of other ABC transporters, such as ABCG1, with the self-renewal potential of osteosarcoma DOX-resistant cells." (PMID 35742867, 2022). "Indeed, ABCG1 was found to be involved in multidrug resistance in osteosarcoma, where it was up-regulated in cells with induced doxorubicin resistance." (PMID 32814794, 2020). "The expression of PDK1 was significantly upregulated in 143B OSCs rather than in 143B non-OSCs, consistent with findings in the OSC population of primary osteosarcoma specimens, along with significant upregulation of stem cell markers, such as SOX2, KLF4, and ABCG1." (PMID 40730548, 2025).
bladder carcinoma (5 papers, 2017 to 2023). "The roles of ABCC5, ABCA8, ABCC10, ABCB10, ABCG1, ATP7B, ABCG2, and mitochondrial SLC25A10 in platinum-receiving urinary bladder cancer patients should be the subject of further investigation." (PMID 36650399, 2023). "There has been no research to date depicting the influence of ABCG1 variability on cisplatin-treated urinary bladder cancer." (PMID 36650399, 2023).
clear cell renal cell carcinoma (5 papers, 2021 to 2025). "Notably, ABCG1 has been reported as a diagnostic marker in clear cell renal cell carcinoma, and LIPG in gastric cancer." (PMID 40804485, 2025). "For example, ABCG1, which is overexpressed in clear cell renal cell carcinoma, has been found to be associated with overall patient survival, indicating its potential as a diagnostic and prognostic biomarker in clear cell renal cell carcinoma." (PMID 35837087, 2022). "Background and Aims: In this study, we analyzed the expression levels of ATP-binding cassette transporter G1 (ABCG1) in clear cell renal cell carcinoma (ccRCC) to assess its significance for early diagnosis and its role in the disease's biological processes." (PMID 40520894, 2025). "However, there is no clear cell renal cell carcinoma vs normal in the five datasets of ABCF1.The result showed that ABCG1 was highly overexpressed in all datasets." (PMID 33825659, 2021).
colon cancer (5 papers, 2018 to 2025). "In aggregate metastatic colon cancer cells, high ABCG1 expression fosters lipid accumulation within extracellular vesicles (EVs), which reduces cytotoxicity and enhances tumor cell survival." (PMID 40520894, 2025). "ABCG1 inhibition by knockdown suppresses tumor growth in a colon tumor mouse model by blocking extracellular vesicle (EV) lipid efflux, thereby leading to the accumulation of EVs, which mediate cellular toxicity." (PMID 34820325, 2021). "Our transcriptomics revealed that ABCG1 was powerfully expressed in rapidly metastatic, aggregative colon cancer cells, in all the ABC transporter family members." (PMID 30364132, 2018). "We showed ABCG1 to be markedly expressed in metastatic colon cancer cells, their tumoroids as well as in subcutaneous tumors." (PMID 30364132, 2018). "This appears highly conceivable, inasmuch as the metastatic colon cancer cells, tumoroids and tumors derived from them express high level of ABCG1." (PMID 30364132, 2018). "Interestingly, ABCG1 and ABCG2 are co-expressed in metastatic colon cancer cells, with ABCG1 influencing ABCG2 expression through the modulation of HIF-1α." (PMID 39850800, 2024). "We also showed that ABCG1 and ABCG2 were co-expressed in the metastatic colon cancer cells." (PMID 30364132, 2018).
glioma (5 papers, 2016 to 2025). A benign or malignant brain and spinal cord tumor that arises from glial cells (astrocytes, oligodendrocytes, ependymal cells). "In agreement with an active role in tumor development, ABCG1 is confirmed to promote glioma cell growth via regulation of ER stress." (PMID 38896016, 2024). "Collectively, these findings establish Abcg1 as a mediator of ER stress-mediated apoptosis and survival in high-grade glioma." (PMID 26981778, 2016). "Collectively, these results establish ABCG1 as another potential biomarker for high-grade glioma survival relevant to future brain tumor therapeutic targeting." (PMID 26981778, 2016). "We have recently shown that human low-grade (pilocytic astrocytoma) glioma specimens exhibit increased ABCG1 expression." (PMID 26981778, 2016). "Formal demonstration of an ubiquitin ligase pathway that coordinately regulates neurofibromin and ABCG1 expression in glioma warrants further investigation." (PMID 26981778, 2016). "Using a total of 159 glioblastoma patients dichotomized by the median of ABCG1 expression, there were no significant survival differences between patients harboring gliomas with low versus high ABCG1 gene expression." (PMID 26981778, 2016). "We have recently shown that ABCG1, an ATP-binding cassette transporter, maintains ER homeostasis and suppresses ER stress-induced apoptosis in low-grade glioma." (PMID 26981778, 2016). "Moreover, the Ku80+ cells in these LGGs also expressed CD133 and ABCG1, markers of glioma stem cells, but were immunonegative for SOX10 and p16 expression, which can be observed in some patient pediatric LGGs." (PMID 35986378, 2022). "In this subtype, one of the signature genetic changes is mutation of the NF1 tumor suppressor gene, which is intriguing, given the prior identification of ABCG1 as a uniquely upregulated transcript in GSCs originating from a mouse model of low-grade glioma harboring biallelic Nf1 gene inactivation." (PMID 26981778, 2016). "As the etiologic mechanisms responsible for ABCG1-mediated suppression of ER stress and glioma survival become elucidated, future therapeutic strategies designed to blocking these adaptations may improve treatment efficacy for this deadly brain malignancy." (PMID 26981778, 2016). "Next, we sought to determine whether ABCG1 expression was associated with clinical outcome (overall survival) in patients with high-grade glioma (GSE16011), the majority of whom did not receive prior chemotherapy." (PMID 26981778, 2016). "Moreover, Abcg1 KD reduced NPcis glioma growth and increased mouse survival in vivo." (PMID 26981778, 2016). "Knockdown of ABCG1 increases and activates BiP and CHOP to break ER hemostasis to promote apoptosis in glioma." (PMID 38896016, 2024). "Leveraging a mouse model of mesenchymal glioblastoma (NPcis), shRNA-mediated Abcg1 knockdown (KD) increased CHOP ER stress protein expression and resulted in greater NPcis glioma cell death in vitro." (PMID 26981778, 2016).
Abdominal obesity (4 papers, 2016 to 2025). Excessive fat around the stomach and abdomen. "Recent studies demonstrated that the methylation of ABCG1, CPT1A, and SREBF1 genes was associated with some cardio-metabolic risk factors including total cholesterol and insulin levels, as well as anthropometric indices of general and abdominal obesity." (PMID 35551677, 2022). "Thus, ABCG1 expression in SAT could be influenced by DNA methylation and associated with abdominal obesity." (PMID 34837967, 2021).
cognitive deficits (4 papers, 2009 to 2020). "As ABCG1 does alter cholesterol homeostasis in the brain, it therefore remains possible that excess ABCG1 may influence neuronal physiology and contribute to the cognitive deficits in DS individuals." (PMID 19239689, 2009). "In humans, we and others have demonstrated that the CSF from mild cognitive impairment (MCI), and AD, patients showed a lower ability to induce ABCA1- and ABCG1-efflux." (PMID 33287338, 2020).
glioblastoma (4 papers, 2016 to 2025). The most malignant astrocytic tumor (WHO grade IV). "Together, these findings demonstrate increased ABCG1 expression in human malignant gliomas, where it is associated with reduced survival in patients harboring the mesenchymal glioblastoma subtype." (PMID 26981778, 2016). "While little is known about ABCG1 in cancer, we demonstrate for the first time that ABCG1 is expressed in both murine and human glioblastoma, where its expression correlates with overall patient survival." (PMID 26981778, 2016). "The fact that attenuated ABCG1 expression significantly prolongs mouse survival following glioblastoma implantation supports a critical role for this protein in tumor maintenance." (PMID 26981778, 2016). "In this report, we demonstrate that ABCG1 expression negatively correlates with survival in patients with glioblastoma of the mesenchymal subtype." (PMID 26981778, 2016). "Following Abcg1 knockdown (45–54% protein reduction) in K1861 and K4622 glioblastoma cells, there was increased CHOP expression (2.3 and 3-fold, respectively) and caspase-3 cleavage (1.5 and 2.2-fold, respectively) relative to controls." (PMID 26981778, 2016). "Herein, we demonstrate that ABCG1 expression is increased in human adult glioblastoma, where it correlates with poor survival in individuals with the mesenchymal subtype." (PMID 26981778, 2016). "However, when the analysis was stratified by glioblastoma molecular subtype, high ABCG1 expression correlated with shorter overall survival only in the mesenchymal subgroup, a subtype characterized by NF1 gene mutation." (PMID 26981778, 2016). "However, in striking contrast, mice receiving Abcg1-shRNA K1861 glioblastoma cells had median survivals of 64 (P < 0.0001) and 98 (P < 0.0001) days, respectively." (PMID 26981778, 2016). "Similarly, increased ABCG1 immunoreactivity was observed in representative tumor specimens from human patients with glioblastoma (n = 16) relative to normal brain controls (n = 7)." (PMID 26981778, 2016). "We evaluated the ability of human A172 glioblastoma astrocytes and SH-SY5Y neurons to mediate cholesterol efflux to CSF under basal conditions and following stimulation of the ABCA1- and ABCG1-dependent pathways." (PMID 39764088, 2024). "Based on the controversial use of ABCG2 as a marker of CSCs and the recent identification of ABCG1 as a critical mediator of LG-GSC survival, we sought to determine whether ABCG1 was important for high-grade (glioblastoma) survival." (PMID 26981778, 2016).
Hypertension (4 papers, 2014 to 2025). The presence of chronic increased pressure in the systemic arterial system. "Thus, we proposed that the status of hypertension might be an important confounder for ABCG1-associated CHD risk in the Chinese population, and the combination of ABCG1 methylation and additional risk factors could provide innovative insight into the risk detection of CHD." (PMID 37507725, 2023). "Interestingly, our results suggested that the association between decreased methylation levels of ABCG1 and CHD only exist in individuals without hypertension." (PMID 37507725, 2023).
ischemic stroke (4 papers, 2017 to 2024). A stroke disorder caused by obstruction of blood flow to the brain, due to thrombotic (local blood clot formation) or embolic (due to a blood clot or other material traveling from another site) event. "The association of the ABCG1 polymorphism with the risk of ischemic stroke in a Chinese population has also been shown." (PMID 39857239, 2024). "At the same time, the hypermethylation status in the promoter region of the ABCG1 gene was associated with ischemic stroke, and this association was more significant in women." (PMID 39857239, 2024). "ABCG1 hypermethylation at the cg02494239 is associated with carotid intima media thickness and ischemic stroke." (PMID 34837967, 2021). "In men, a higher risk of ischemic stroke was found in Q4 group of cg02494239 methylation in ABCG1 compared with Q1 group (OR = 6.654, 95% CI 1.094–40.476, P = 0.040)." (PMID 31823830, 2019). "However, little is yet known about an epigenetic impact of ABCG1 and APOE on the development of ischemic stroke." (PMID 31823830, 2019). "The aim of this study was to explore whether DNA methylation loci located in the ATP-binding cassette G1 (ABCG1) and apolipoprotein E (APOE) genes, both involved in the metabolism of lipids in the body, are related to ischemic stroke, using the Fangshan/Family-based Ischemic Stroke Study in China." (PMID 31823830, 2019).